ALK (ALK receptor tyrosine kinase)
Diseases named in the same sentence as ALK in open-access papers (continued):
Sharing a sentence is not in itself a finding about the gene and the disease.
anaplastic large cell lymphoma (continued). "•Clinicopathological correlation is imperative in the diagnosis of leukemic phase ALK-negative anaplastic large cell lymphoma." (PMID 31871676, 2020). "•Leukemic phase ALK-negative anaplastic large cell lymphoma progresses rapidly if the diagnosis is delayed." (PMID 31871676, 2020). "We present the case of a 65-year-old man, simultaneously diagnosed with ALK-negative anaplastic large cell lymphoma with extranodal localization in the gastrocnemius muscle (stage 1AE) and IgG lambda multiple myeloma (ISS 2, Durie-Salmon stage 3A)." (PMID 32509362, 2020). "Of note, MYC with STAT3 transcriptionally regulates PD-L1 in ALK-negative anaplastic large cell lymphoma (ALCL)." (PMID 32549409, 2020). "Nodal PTCL consist of peripheral TCL not otherwise specified (PTCL-NOS), angioimmunoblastic TCL (AITK), and anaplastic large cell lymphoma (ALCL): ALK positive and ALK negative." (PMID 33384022, 2020). "Breast implant‒associated anaplastic large cell lymphoma (BIA-ALCL), first reported in 1997, is a CD30-positive, anaplastic lymphoma kinase (ALK) ‒negative T-cell lymphoma." (PMID 33371292, 2020). "Nearly 30 different ALK fusion protein partners have been described, with echinoderm microtubule-associated protein-like 4 (EML4) and nucleophosmin (NPM) being the most prevalent in NSCLC and anaplastic large cell lymphoma (ALCL) occurring in 3% to 5% and more than 50%, respectively." (PMID 31731495, 2019). "Similarly, crizotinib also showed therapeutic response in ALK-fusion-positive IMT patients and pediatric patients with anaplastic large cell lymphoma and IMT." (PMID 29455642, 2018). "Anaplastic lymphoma kinase (ALK) fusion proteins are oncogenic and are expressed in anaplastic large cell lymphomas (ALCLs) and other tumors, but not in normal tissues." (PMID 30510968, 2018). "Records of 600 PTCL patients diagnosed between 1999 and 2014 were analyzed including PTCL not otherwise specified (PTCL-NOS, 174 patients), angoimmunoblastic T-cell lymphoma (AITL, 144), ALK+anaplastic large cell lymphoma (ALCL, 74), ALK-ALCL, extranodal NK-cell lymphoma (ENKL, 54), or others." (PMID 29538376, 2018). "The reactivation of ancient LTR has also been associated with the novel oncogenic transcription of ERBB4 in ALK-negative anaplastic large cell lymphoma (ALCL)." (PMID 28471386, 2017). "Anaplastic lymphoma kinase (ALK) belongs to the insulin receptor kinase subfamily of receptor tyrosine kinases, and was originally identified as a fusion protein with nucleophosmin (NPM) in anaplastic large cell lymphoma (ALCL)." (PMID 28030793, 2017). "Regarding the histology, 10 (50 %) patients had PTCL not otherwise specified (PTCL-NOS), 9 (45 %) patients had angioimmunoblastic T-cell lymphoma (AITL), and 1 (5 %) patient had anaplastic large cell lymphoma (ALCL) anaplastic lymphoma kinase (ALK) negative." (PMID 27071522, 2016). "Ectopic coexpression of ERBB4 and COL29A1 genes was detected in 24 % of ALK-negative anaplastic large cell lymphoma (ALCL) patients." (PMID 26949423, 2016). "Meanwhile, over 80 cases of anaplastic lymphoma kinase (ALK)-negative anaplastic large cell lymphoma have been reported in patients with SBIs and it has been accepted as a new clinical entity." (PMID 27634631, 2016). "The patient was diagnosed with stage 4 ALK negative anaplastic large cell lymphoma after splenectomy due to uncontrolled splenic hemorrhage." (PMID 25705530, 2015). "Anaplastic lymphoma kinase (ALK) is one of the insulin receptor superfamily of RTKs, and it was firstly identified as a result of cloning the nuclear protein nucleophosmin (NPM)–ALK fusion gene in anaplastic large-cell lymphomas." (PMID 25193856, 2014). "We present the case of a patient with ALK-negative anaplastic large cell lymphoma who presented with SCLS as the initial manifestation of her lymphoma." (PMID 22953081, 2012).
anaplastic large cell lymphoma (continued). "The association of anaplastic lymphoma kinase (ALK) negative anaplastic large cell lymphoma (ALCL), a very rare form of primary breast lymphoma, with silicone-filled breast implants has been suggested and several case reports supported this proposal, especially in Western countries." (PMID 25734044, 2012). "It stratified anaplastic large cell lymphomas (both ALK positive and ALK negative) and PTCL-NOS into two prognostic groups." (PMID 21188274, 2010). "Ninety-six percent of ALK+ and 40% of ALK– anaplastic large-cell lymphomas also lacked expression of the CD3 antigen, compared with 29% of peripheral T-cell lymphomas NOS and 20% of AILT." (PMID 16623775, 2006). "ALK expression can rarely be seen in anaplastic large-cell lymphoma limited to the skin; there is currently no substitute for careful staging and follow-up." (PMID 16623775, 2006). "Research on systemic and cutaneous Dual Specificity Phosphatase-22 (DUSP-22) rearrangements in Anaplastic Lymphoma Kinase (ALK)-negative Anaplastic Large Cell Lymphoma (ALCL) has demonstrated positive CD58 expression, correlating with immune identification of the tumor and a favorable prognosis." (PMID 40365344, 2025). "Given the rarity of phenotypical shift in this direction in CTCL, the following report is the first of its kind to specifically describe this CD8+ to CD4+ immunophenotypic shift in MF with concurrent large cell transformation to ALK-negative anaplastic large cell lymphoma." (PMID 40166794, 2025). "ALK rearrangements, including EML4-ALK fusions, are involved in subsets of non-small cell lung cancer (NSCLC) and anaplastic large cell lymphoma (ALCL)." (PMID 40547482, 2025). "The crizotinib-coated pellet product is approved in the US for the treatment of relapsed or refractory, systemic anaplastic large cell lymphoma (ALCL) and unresectable, recurrent, or refractory inflammatory myofibroblastic tumor (IMT) that is ALK-positive." (PMID 39204372, 2024). "Lymph node biopsy showed intermediate to large atypical monomorphic lymphocyte cells with ALK, CD30, CD5, CD3, CD45, and BCL-2 (weak positive) positivity and Ki-67-95%, suggestive of anaplastic large cell lymphoma (ALCL)." (PMID 38650799, 2024). "Peripheral T-cell lymphomas (PTCLs) are a heterogeneous group of non-Hodgkin lymphomas including PTCL-not otherwise specified (PTCL-NOS), angioimmunoblastic T-cell lymphoma (AITL), and anaplastic lymphoma kinase (ALK)-positive or -negative anaplastic large-cell lymphoma (ALCL)." (PMID 37675232, 2023). "Anaplastic lymphoma kinase (ALK), as a member of tyrosine receptor kinase family, was first identified as a fusion partner in anaplastic large cell lymphoma (ALCL) in 1994." (PMID 37342628, 2023). "DUSP22 translocations are relatively specific for ALK-negative anaplastic large cell lymphomas." (PMID 35330161, 2022). "Furthermore, comparative genomic hybridization revealed that ALK-negative anaplastic large cell lymphoma differs from ALK-positive anaplastic large cell lymphoma and other peripheral T cell lymphomas in terms of genetic characteristics." (PMID 35406421, 2022). "In addition, clonal chromosomal translocations of the DUSP22-IRF4 locus on 6p25.3 (DUSP22 rearrangements) have been observed in around 30% of systemic ALK-negative anaplastic large cell lymphomas." (PMID 35406421, 2022). "The anaplastic morphology and the intrasinusoidal growth observed in some cases of PEL in combination with the possible aberrant T-cell marker expression and strong CD30 positivity may suggest a diagnosis of ALK-negative anaplastic large cell lymphoma (ALCL)." (PMID 34572754, 2021). "In anaplastic large cell lymphoma (ALCL), oncogenic NPM/ALK signaling is mediated by several pathways, which play major roles in lymphomagenesis by controlling key cellular processes such as cell cycle progression." (PMID 34747369, 2021).
anaplastic large cell lymphoma (continued). "A total of nine isolated case reports of anaplastic large cell lymphoma with cardiac involvement were found in the English-language literature, and a widespread cardiac and thymic infiltration by the systemic ALK-positive anaplastic large cell lymphoma has not been documented." (PMID 33968818, 2021). "Activating mutations in JAK1 are found in CTCL, natural killer cell lymphoma (NKCL) and large granulocytic leukemia (LGL), as well as in 20% of ALK-negative anaplastic large cell lymphoma (ALCL), and treatment with ruxolitinib reduced tumor growth in an ALK-negative ALCL PDX model in vivo." (PMID 34066732, 2021). "It reduced cell proliferation in ALK-positive anaplastic large cell lymphoma (ALCL), which is frequently characterized by the fusion protein nucleophosmin (NPM)-ALK." (PMID 34885651, 2021). "In addition to IL-10, IFN γ, IL-8, IL-17, IL-23, monocyte chemoattractant protein-1 and macrophage inflammatory protein-1β, and RANTES negatively also have negative effects on clinical prognosis in patients with ALK- anaplastic large cell lymphoma." (PMID 33154947, 2020). "These were peripheral T-cell lymphomas, including ALK-positive anaplastic large cell lymphoma, anaplastic large cell lymphomas (T and null cell types), primary cutaneous anaplastic large cell lymphoma and anaplastic large cell lymphomas not specified and without T- and B-cell markers." (PMID 32344893, 2020). "SupM2, an ALK-positive anaplastic large cell lymphoma cell line, was used as a negative control." (PMID 30791634, 2019). "In fact, ALK was first discovered in anaplastic large cell lymphoma (ALCL) in the form of a fusion protein, NPM1-ALK." (PMID 30941048, 2019). "There has been a significant increase in targeted therapies available for the management of ALK-positive cancers including NSCLC, inflammatory myofibroblastic tumors (IMT), and anaplastic large cell lymphoma (ALCL)." (PMID 27049722, 2016). "We report a 43-year-old male patient who was diagnosed as TA-TMA after allogeneic progenitor cell transplantation for a progressive ALK negative anaplastic large cell lymphoma and responded to eculizumab with dramatically improving neurological status and renal function." (PMID 25705530, 2015). "Notably, a previous study demonstrated that lymphoma cells were strongly positive for ALK in a cytoplasmic granular staining pattern, which was different to the cytoplasmic and/or nuclear pattern characteristics of the T/null anaplastic large cell lymphoma (ALCL)." (PMID 25009592, 2014). "K-299 and SUDHL, two anaplastic large cell lymphoma (ALCL) cell lines that express NPM-ALK and are dependent on ALK for growth, were used to evaluate the efficacy of GTx-186 and crizotinib." (PMID 24386191, 2013). "Anaplastic large cell lymphomas are CD30+ and EMA+ and may show ALK positivity." (PMID 23388086, 2013). "Therefore, it is apparent that a great majority of T-cell lymphoma patients, with the exception of ALK-positive anaplastic large cell lymphoma, have a dismal prognosis irrespective of their prognostic scores." (PMID 21188274, 2010). "It was shown to produce superior remission rate (complete remission of 71%) when alemtuzumab was combined with CHOP as frontline treatment in a group of 24 patients with peripheral T-cell lymphomas (none of the them were ALK-positive anaplastic large cell lymphoma)." (PMID 21188274, 2010). "However, 31% of the patients were anaplastic large cell lymphomas, and the status of ALK expression was not known." (PMID 21188274, 2010).
anaplastic large cell lymphoma (continued). "Postoperative pathology of the left cerebellum indicated anaplastic large cell lymphoma (ALCL), anaplastic lymphoma kinase (ALK) negative; cyclophosphamide 300 mg + dexamethasone 5 mg was administered." (PMID 40777017, 2025). "A lymph node biopsy confirmed anaplastic large cell lymphoma (ALCL), anaplastic lymphoma kinase (ALK)-negative, characterized by strong CD30 expression." (PMID 39956030, 2025). "Other types of mature T cell lymphomas have more specific presentations such as CD30 positive T-cell LPD (commonly seen in the skin) and anaplastic large cell lymphoma that may be ALK-positive (commonly in the lymph node) or ALK-negative (present in either the skin or lymph node)." (PMID 39873807, 2025). "In the context of our observed large cell transformation, we established the diagnosis as one of the ALK-negative anaplastic large cell lymphoma (ALCL) subtypes." (PMID 40166794, 2025). "Anaplastic Large Cell Lymphoma (ALCL) is a rare and aggressive T-cell lymphoma, classified into ALK-positive and ALK-negative subtypes, based on the presence of chromosomal translocations involving the ALK gene." (PMID 39478125, 2024). "Anaplastic large cell lymphomas (ALCL) are a group of sporadic malignancies that generally have an aggressive clinical course, especially the subtype of anaplastic lymphoma kinase (ALK)-negative ALCL." (PMID 38425329, 2024). "This study reports a rare case of concurrent invasive lobular carcinoma (ILC) of the breast and ALK-negative anaplastic large cell lymphoma (ALCL) detected during sentinel lymph node biopsy (SLNB)." (PMID 39610919, 2024). "Given that CD30 positivity is observed in a significant proportion of EBV+ NT/NKCL cases, it can be challenging to distinguish it from ALK-negative anaplastic large cell lymphoma (ALCL)." (PMID 38921179, 2024). "ALK-negative anaplastic large cell lymphomas (ALCL) are clinically and molecularly quite heterogeneous." (PMID 38638855, 2024). "The most common TCL subtypes were T-follicular helper (TFH) TCL (25%), followed by peripheral T-cell lymphoma not otherwise specified (PTCL-NOS) (21%) and anaplastic lymphoma kinase (ALK) negative anaplastic large cell lymphoma (ALCL) (14%)." (PMID 39410047, 2024). "Anaplastic large cell lymphoma (ALCL) of the ALK-negative (ALK−) type typically affects both lymph nodes and extranodal tissues; however, extranodal involvement tends to be less frequent than ALK+ ALCL cases." (PMID 37443818, 2023). "An ALK-negative anaplastic large cell lymphoma (ALCL) typically affects lymph nodes or tissues, with solid sheets of cancerous cells replacing their original architecture." (PMID 37443818, 2023). "Other FRK‐related fusion genes, including CAPRIN1::FRK, PABPC1::FRK, and MAPK9::FRK, have been identified in ALK‐negative anaplastic large cell lymphoma (ALCL)." (PMID 37601849, 2023). "The majority of cases fall under angioimmunoblastic T‐cell lymphoma (AITL), anaplastic large cell lymphoma (ALCL; ALK+ or ALK‐ forms), and PTCL‐not otherwise specified (PTCL‐NOS), the latter forming a catch‐all group of unclassifiable PTCL." (PMID 35510955, 2022). "Five classical Hodgkin lymphoma (cHL) patients and 1 anaplastic lymphoma kinase (ALK)-negative anaplastic large cell lymphoma (ALCL) patient were enrolled." (PMID 36253833, 2022). "Nodal PTCLs include ALK-positive (ALK+) and ALK-negative (ALK−) anaplastic large cell lymphoma (ALCL); nodal T-cell lymphoma with T follicular helper (TFH) cell origin; and PTCL, not otherwise specified (PTCL-NOS)." (PMID 36010351, 2022). "Similarly, the oncogenic fusion tyrosine kinase, nucleophosmin/anaplastic lymphoma kinase (NPM/ALK), phosphorylates PSF on Y293, which is located near the RRM1 domain (residues 299–363) in the N-terminus and increases the ability of PSF to bind RNA in anaplastic large-cell lymphoma." (PMID 34638572, 2021).
anaplastic large cell lymphoma (continued). "The main differential diagnosis for intravascular large B-cell lymphoma includes intravascular natural killer cell (NK) lymphomas, intravascular T-cell lymphomas, and intralymphatic ALK-negative anaplastic large cell lymphomas (ALCL)." (PMID 33322508, 2020). "Anaplastic lymphoma kinase is a member of the insulin receptor protein−tyrosine kinase superfamily, originally described as a nucleophosmin (NPM)-ALK fusion form in an anaplastic large cell lymphoma (ALCL) cell line." (PMID 33352844, 2020). "The most prevalent PTLCs are PTCL not otherwise specified (NOS), angioimmunoblastic T-cell lymphoma (AITL), anaplastic lymphoma kinase–negative (ALK− ALCL), and anaplastic lymphoma kinase-positive anaplastic large cell lymphoma (ALK+ ALCL)." (PMID 32188095, 2020). "Multiple outside expert consultations rendered a consensus diagnosis of ALK-negative anaplastic large cell lymphoma (ALCL)." (PMID 32547956, 2020). "Breast implant-associated anaplastic large cell lymphoma (BIA-ALCL) is a distinct CD30+, anaplastic lymphoma kinase (ALK) negative T-cell lymphoma." (PMID 31316085, 2019). "Anaplastic large cell lymphoma (ALCL) is a very rare breast implant-associated T-cell lymphoma that is CD30+ and anaplastic lymphoma kinase (ALK) negative." (PMID 29649133, 2018). "The differential diagnoses for ALK-positive tumors of the skin include ALK-positive anaplastic large cell lymphoma (ALK+ALCL) with or without systemic involvement and Spitz tumors with ALK fusion." (PMID 29747676, 2018). "Anaplastic Large Cell Lymphoma (ALCL) is a clinical and biological heterogeneous disease including systemic ALK positive and ALK negative entities." (PMID 28061468, 2017). "The original discovery of ALK was in 1994, when Morris and colleagues first characterized the ALK gene as a fusion partner of nucleophosmin (NPM), in the NPM-ALK translocation found in a subset of anaplastic large cell lymphoma (ALCL)." (PMID 27049722, 2016). "Anaplastic large cell lymphoma (ALCL) is the most likely to be confused with EIMS, because both tumors have an overlapping immunophenotype and cytogenetic feature, including reactivity for CD30, ALK and SMA, and the presence of ALK rearrangement." (PMID 27460384, 2016). "Diagnostic categories that we considered included a composite lymphoma with DLBCL and ALK negative T/null anaplastic large cell lymphoma (ALCL) or a lymphocyte depleted Hodgkin-like lymphoma." (PMID 23738160, 2013). "ALK-positive anaplastic large cell lymphomas (ALCL) express low levels of miR-29a, whose downregulation requires an active NPM-ALK kinase, and may probably also be due to methylation repression." (PMID 23431463, 2013). "After directly mixing individual siRNAs and aptamers with PEI to form an average ∼140 nm hydrodynamic diameter, the targeted nanocomplexes specifically silenced ALK gene expression and induced growth arrest and apoptosis in CD30-expressing anaplastic large cell lymphoma (ALCL) cells." (PMID 23130020, 2012). "In this study, we tested a functional RNA nanocomplex which exclusively targets and affects human anaplastic large cell lymphoma (ALCL) by taking advantage of the abnormal expression of CD30, a unique surface biomarker, and the anaplastic lymphoma kinase (ALK) gene in lymphoma cells." (PMID 21281497, 2011). "Singh and colleagues also reported that PI3K/AKT contributes to activation of the HH/GLI1 signaling pathway in ALK-positive anaplastic large cell lymphoma (ALCL), but not in ALK-negative ALCL." (PMID 19575820, 2009). "The 2016 World Health Organization classification defines 29 PTCL subtypes, including PTCL-not otherwise specified (PTCL-NOS), angioimmunoblastic T-cell lymphoma (AITL), anaplastic lymphoma kinase (ALK) positive anaplastic large cell lymphoma (ALK+ALCL), ALK negative ALCL (ALK-ALCL) and others." (PMID 41394820, 2025).